CXCR2 (C-X-C motif chemokine receptor 2)
Diseases named in the same sentence as CXCR2 in open-access papers (continued):
Sharing a sentence is not in itself a finding about the gene and the disease.
pulmonary fibrosis (14 papers, 2013 to 2024). Chronic progressive interstitial lung disorder characterized by the replacement of the lung tissue by connective tissue, leading to progressive dyspnea, respiratory failure, or right heart failure. "Bleomycin-induced Cxcl1 production in lungs and Cxcl1 levels correlated with neutrophilic airway inflammation in mice preceding pulmonary fibrosis which were attenuated by the Cxcr2 antagonists or endothelial glycosaminoglycans antagonism." (PMID 39768150, 2024). "In mice, antagonism of Cxcr1 and Cxcr2 reduces pulmonary fibrosis, acting on endothelial cells, neutrophils, and fibroblasts, and mediating neutrophilic lung inflammation, angiogenesis, and fibrogenesis." (PMID 39768150, 2024). "The genetic Cxcl1 deletion or pharmaceutical inhibition of Cxcl1 binding to Cxcr2 by Reparixin ameliorated the exacerbation of pulmonary fibrosis induced by particulate matter." (PMID 39768150, 2024). "Reparixin, an inhibitor of IL-8 receptor such as CXCR1/2, inhibits neutrophil influx, fibrogenic cytokine, and decreases pulmonary fibrosis by blocking CXCR2." (PMID 33706759, 2021). "Mice deficient in P2Y2 fail to recruit neutrophil and have attenuated fibrosis in response to bleomycin challenge and treatment of mice with a CXCR2 antagonist reduced airway neutrophil transmigration and pulmonary fibrosis." (PMID 32102985, 2020). "Further, genetic KC deletion or pharmaceutical inhibition of KC binding to CXCR2 with reparixin ameliorated the PM-induced increased severity of pulmonary fibrosis." (PMID 31905700, 2019). "The relevant roles of KC and its receptor, CXCR2, in the development of pulmonary fibrosis induced by bleomycin have also been demonstrated." (PMID 31905700, 2019). "It has been shown that Ccl22 and Cxcr2 promote the pathogenesis of pulmonary fibrosis." (PMID 38162655, 2023). "In addition, research has shown that CXCR2-mediated neutrophil recruitment is essential for lung fibrosis, and that blocking CXCR2 can reduce lung fibrosis." (PMID 34055876, 2021). "Indeed, we have previously evaluated the role of CXCR1 and CXCR2 in the context of experimental pulmonary fibrosis." (PMID 33123138, 2020). "Evidence suggests that CXCR2 mediates pulmonary fibrosis after bleomycin instillation in mice." (PMID 32630825, 2020). "Moreover, our study demonstrated that nintedanib downregulated Ly6G and CXCR2 expression levels in circulating neutrophils while upregulating GRK2 expression in pulmonary fibrosis." (PMID 32630825, 2020). "Therefore, the CXCR1 and CXCR2 activation may contribute to the pulmonary fibrosis in human and mouse models." (PMID 33123138, 2020). "Indeed, Cxcr2 antagonism attenuated lung angiogenesis and fibrosis in mice challenged with bleomycin, supporting that Cxcl2 is an important angiogenic factor that may regulate pulmonary fibrosis development in mice." (PMID 39768150, 2024). "Taken together, aesculetin may antagonize pulmonary fibrosis and alveolar epithelial barrier disruption stimulated by the infiltration of monocyte-derived macrophages, which is typical of PHMG toxicity, involving interaction of IL-8 and CXCR2." (PMID 32752252, 2020). "Nintedanib mediated a downregulation of chemokine (C-X-C motif) receptor 2 (CXCR2) and very late antigen 4 (VLA-4) expression, as well as an upregulation of G protein-coupled receptor kinase 2 (GRK2) activity in peripheral blood neutrophils in BLM-induced pulmonary fibrosis." (PMID 32630825, 2020). "Taken together, aesculetin may antagonize pulmonary fibrosis and alveolar epithelial barrier disruption triggered by infiltration of monocyte-derived macrophages—which is typical of PHMG toxicity—involving interaction of MIP-2 and CXCR2." (PMID 32752252, 2020). "Lack of CXCR2, the receptor for CXCL3/KC, one of the main neutrophil chemotactic agents in mice, resulted in decreased lung fibrosis along with decreased accumulation of neutrophils in the airways." (PMID 24970330, 2014).
viral infection (14 papers, 2005 to 2025). "All three chemokines share one receptor, CXCR2 (C-X-C Motif Chemokine Receptor 2), and have been implicated in responses to viral infection, hematopoietic malignancies and vascular disease." (PMID 35915123, 2022). "Mice treated with CXCR2 neutralizing antiserum were incapable of controlling viral replication, and 100% of all infected mice succumbed to viral infection within 11 days and this was associated with an impaired ability to control CNS viral replication." (PMID 24987333, 2014). "While investigating the involvement of the CXCL1-3/CXCR2 axis in dsRNA (Poly IC)-induced viral infection of the lung, it was discovered that the expression of CXCR2 and its ligands, CXCL1 and CXCL2/3, tallied with the recruitment of neutrophils to the lung." (PMID 36164329, 2022). "It was associated with higher neutrophil recruitment by increased levels of CXCL1/2, CXCR2, and interleukin 1β (IL-1β) at a later stage of viral infection." (PMID 36005818, 2022). "Nevertheless, CXCR2-directed neutrophil infiltration into the CNS is a key determinate for subsequent inflammatory cell infiltration in a variety of CNS models of viral infection, demyelination, and autoimmunity." (PMID 24987333, 2014). "Collectively, these data suggest that CXCR2, during chronic viral infection of the CNS, prevents oligodendrocyte apoptosis and promotes clinical recovery from viral induced demyelination." (PMID 24987333, 2014). "CXCL8 could mediate productive infection of HIV-1 in cells via receptors CXCR1 and CXCR2 and also could be induced by Porcine epidemic diarrhea virus nsp4 which in turn inhibited virus infection." (PMID 35937300, 2022). "CXCL1 expression was localized to GFAP+ astrocytes within the white matter, suggesting that CXCR2, besides attracting neutrophils during early acute viral infection, may also alternatively function during chronic demyelination." (PMID 24987333, 2014). "Since CXCL1 and CXCL2/3, acting through CXCR2, are potent neutrophil chemoattractants, we investigated their role in dsRNA-induced lung injury, where dsRNA (Poly IC) is a well-described synthetic agent mimicking acute viral infection." (PMID 15921526, 2005). "During viral infection, IFN can suppress CXCR2-mediated neutrophil recruitment into the sensory ganglia." (PMID 27721573, 2016). "Clinical trials using CXCR1 and CXCR2 inhibitors revealed that they are successful in treating patients with chronic diseases (e.g., COPD), whereas their use can be detrimental in patients with viral infection." (PMID 32733442, 2020). "Notably, CXCR2 neutralization did not alter the peripheral generation of virus-specific T cells, indicating that the increased mortality and diminished ability to control viral infection within the CNS is likely associated with the dampened access of T cells into the CNS parenchyma." (PMID 24987333, 2014). "With regards to JHMV infection, depletion of PMNs increases mortality due to abrogated BBB permeabilization and subsequent diminished T cell infiltration into the CNS, however the relationship between CXCR2 signaling and PMN migration during viral infection of the CNS has yet to be determined." (PMID 19893623, 2009). "Interestingly, a few studies have shown that the absence of type I IFNs results in CXCR2-driven neutrophil accumulation in the lungs or sensory ganglia following viral infections." (PMID 29352287, 2018). "In addition, blocking or silencing of CXCR2 signaling mutes inflammation and tissue damage in mouse models in which PMN infiltration is critical to disease initiation, including SCI, inflammatory demyelination, bacterial infection of the CNS, and viral infection or injury to the lung." (PMID 19893623, 2009). "In this study, we hypothesized that the interaction between CXCR2 and ELR-positive CXC chemokines expressed during dsRNA-induced lung inflammation is critical in mediating neutrophil recruitment, a pivotal process required for dsRNA induced lung injury in viral infections." (PMID 15921526, 2005).
Insulin resistance (13 papers, 2009 to 2025). Increased resistance towards insulin, that is, diminished effectiveness of insulin in reducing blood glucose levels. "Animals treated with anti-CXCL5 or those with C-X-C motif chemokine receptor 2 (CXCR2) knockouts exhibited reduced insulin resistance." (PMID 40216734, 2025). "In this study, we have also evaluated the impact of CXCR2 inhibition by ladarixin on relevant pathways of glucose metabolism and insulin resistance." (PMID 34571976, 2021). "Among pro-inflammatory chemokine, CXCL5, a chemokine ligand of CXCR2, has been related to insulin resistance and obesity-related disorders." (PMID 34571976, 2021). "Studies have shown that CXC motif chemokine ligand 5 (CXCL5) and its cognate chemokine receptor CXCR2 also support development of insulin resistance." (PMID 24741577, 2014). "In diet-induced obese mice, IL-8 receptor (CXCR2) knockout prevents macrophage recruitment in adipose tissue and insulin resistance." (PMID 24918199, 2014). "Genes such as sirtuin-1 (SIRT1), C-reactive protein (CRP), C-X-C motif chemokine receptor 2 gene (CXCR2), as well as chemokines and interleukins such as interleukin 12 (IL12A) and C-X-C motif chemokine ligand 8 (CXCL8), are strongly associated with insulin resistance and T2D." (PMID 38674857, 2024). "Here we demonstrate that a CXCR2 antagonist, AZD5069, as a single agent, was beneficial in the prevention of progression of insulin resistance and liver pathology reminiscent of NASH/NAFLD." (PMID 35831885, 2022). "Our findings support the hypothesis that chronic inhibition of CXCR2 signals may delay the onset and prevent the development of TNF-a induced insulin resistance and related complications." (PMID 39627194, 2024). "Other cell types including macrophages also respond to IL-8 as lack of IL-8 receptor CXCR2 protects from adipose macrophage recruitment and insulin resistance in diet-induced obese mice." (PMID 23637889, 2013).
lung adenocarcinoma (13 papers, 2013 to 2025). A carcinoma that arises from the lung and is characterized by the presence of malignant glandular epithelial cells. "Samples from humans with lung adenocarcinoma showed that CXCR2 expression was associated with poor prognosis, a history of smoking, as well as RAS pathway activation." (PMID 39982274, 2025). "In lung adenocarcinoma, CXCR2 is a poor prognostic marker and its expression is associated with tumor invasion and metastasis." (PMID 33814009, 2021). "Equivalent results were shown in the NSCLC lung adenocarcinoma cell line, where knocking out CXCR2 or blocking with a small molecule antagonist decreased invasion and metastasis of cells expressing CXCR2." (PMID 39982274, 2025). "In lung adenocarcinoma, up-regulation of CXCR2 in tumor cells promotes invasion and metastasis, which results in a poor prognosis." (PMID 35963638, 2022). "The results of this study indicate that CXCR2 is overexpressed in the tumor tissues of patients with lung adenocarcinoma and squamous cell lung cancer and high expression of CXCR2 is associated with poor prognosis." (PMID 33814009, 2021). "Immunohistochemical analysis of CXCR2 was performed on the microarray of tumor tissues of clinical lung adenocarcinoma and lung squamous cell carcinoma patients." (PMID 33814009, 2021). "The result showed that CXCR2 was positive in both tumor cells and tumor stroma of most lung adenocarcinoma and squamous cell carcinoma." (PMID 33814009, 2021). "In previous studies, researchers have demonstrated that treatment with a CXCR2 antagonist (SB225002) inhibits the tumour cell invasive properties of lung adenocarcinomas and suppresses the tumour growth of intrahepatic cholangiocellular carcinomas." (PMID 29665837, 2018). "It has recently been shown that CXCR2 expression in tumor cells is a poor prognostic factor and promotes invasion and metastasis in lung adenocarcinoma." (PMID 24321240, 2013). "The role of CXCL5/CXCR2 on tumor cells themselves has been less studied, but a recent study suggests an important role of CXCL5 in lung adenocarcinomas in promoting invasion and metastasis." (PMID 25076207, 2014). "Promoter hypermethylation of the CXCR2 axis has been determined in NSCLC and may be an important therapeutic target in lung adenocarcinoma." (PMID 36611170, 2023).
neutropenia (13 papers, 2012 to 2026). A decrease in the number of neutrophils found in the blood. "Another example is the homozygous Cxcr2 line with several phenotypes involving B cell and T cell disturbances and the corresponding human orthologue CXCR2 associated to Autosomal recessive, severe congenital neutropenia due to CXCR2 deficiency (ORPHA:420699)." (PMID 31127358, 2019). "Similarly, loss-of-function (LOF) variants in CXCR2 also result in neutropenia, increased infection susceptibility and myelokathexis." (PMID 41451234, 2025). "The precise prevalence or incidence of CXCR2 deficiency linked to neutropenia in the general population is currently unknown." (PMID 41451234, 2025). "However, systemic administration of CXCR2 inhibitors increases the risk of developing neutropenia, potentially leading to adverse effects in cancer patients with compromised immune systems." (PMID 36986488, 2023). "It is important to highlight that PXS-4728A diminished, but did not abolish neutrophil influx to the lung and did not change neutrophil counts in circulation, affording a more beneficial approach to lung inflammation than CXCR2 blockers, that have been shown to cause neutropenia." (PMID 25889951, 2015). "Despite these promising features, the safety of systemic CXCR2 inhibitors remains questionable as these small molecule drugs disrupt neutrophil chemotaxis and activation, resulting in an increased risk of developing neutropenia in cancer patients who already suffer from a compromised immune system." (PMID 36986488, 2023). "Blood smear analysis corroborated these results, confirming that the CXCR2 LOF mice exhibited circulating neutropenia, which was reversed by CXCR4 antagonism." (PMID 41451234, 2025). "However, despite these encouraging findings, there remains a gap in understanding whether CXCR4 antagonists can effectively address peripheral blood neutropenia, abnormal BM neutrophil counts, and infection susceptibility specifically in patients harboring CXCR2 LOF variants." (PMID 41451234, 2025). "Our results further support this finding, demonstrating that chronic treatment with a CXCR4 antagonist increased blood neutrophil counts and corrected peripheral blood neutropenia in CXCR2 LOF mice." (PMID 41451234, 2025). "Treatment with the CXCR2 antagonist resulted in profound peripheral blood neutropenia, evidenced by a ~65% reduction in circulating neutrophil levels compared to control mice." (PMID 41451234, 2025). "Conversely, patients with loss-of-function (LOF) variants in CXCR2 exhibit many phenotypic traits similar to those seen in individuals with CXCR4 GOF mutations, such as neutropenia, increased susceptibility to infections and myelokathexis." (PMID 41451234, 2025). "Altogether, these results indicate that CXCR4 antagonism corrected peripheral blood neutropenia in CXCR2 LOF mice." (PMID 41451234, 2025). "Chemotherapy, for example, can cause life-threatening neutropenia as a side effect, and blocking neutrophil migration via CXCR1 and CXCR2, and inhibiting G-CSF, inhibit neutrophil function." (PMID 35205709, 2022). "Importantly, CXCR4 antagonist treatment led to a significant increase in absolute neutrophil count and corrected circulating neutropenia in CXCR2 LOF mice." (PMID 41451234, 2025). "To investigate whether CXCR4 antagonism can correct peripheral blood neutropenia, a common clinical phenotype observed in patients with CXCR2 LOF variants, we initially considered using Cxcr2 knockout (Cxcr2-/-) mice." (PMID 41451234, 2025). "Unexpectedly, the proportions of circulating patient neutrophils at baseline expressing CXCR1 and CXCR2 were reduced in patients, which may reflect distorted distribution dynamics, and might also contribute to neutropenia-dependent immunodeficiency." (PMID 40330596, 2025). "Additionally, the ability of G-CSF to mobilize neutrophils and correct blood neutropenia in a Cxcr2 -/- mixed BM chimeras mouse model was significantly compromised." (PMID 41451234, 2025).
neutropenia (continued). "Future studies will be required to address whether CXCR4 antagonists can correct peripheral blood neutropenia in a Cxcr2-/- mixed BM chimeras and patients with CXCR2 LOF." (PMID 41451234, 2025). "In contrast, Cxcr2-/- mixed BM chimeras exhibit patient-like features, including circulating neutropenia and BM myelokathexis, but present challenges like immune interactions, donor cell variability, and complications from conditioning regimens and immunosuppression." (PMID 41451234, 2025). "Our findings demonstrate that CXCR4 antagonism effectively corrected peripheral blood neutropenia, restored reduced splenic neutrophil counts, normalized mature neutrophil accumulation in BM, and normalized the M/E ratio and MK-like phenotype in BM of CXCR2 LOF mice." (PMID 41451234, 2025). "It has been reported that CXCR2 inhibition may lead to transient, reversible neutropenia." (PMID 31924241, 2020). "While CXCR4 antagonism corrected peripheral blood neutropenia in CXCR2 LOF mice, it did not appear to affect the count of red blood cells or platelets in both CXCR2 LOF and control mice, consistent with a previous report." (PMID 41451234, 2025). "While some patients harboring CXCR2 mutations show myelokathexis or neutropenia, the absence of other features of WHIM syndrome, indicate that this CXCR2 deficiencies have characteristics distinct from those of WHIM." (PMID 39035006, 2024). "Notably, the correction of peripheral neutropenia observed in our CXCR2 LOF mice following CXCR4 antagonist treatment suggests a promising alternative for patients with CXCR2 LOF who do not adequately respond to G-CSF." (PMID 41451234, 2025). "Importantly, subjects did not develop low neutrophil counts or overt neutropenia, as has been reported with other CXCR2 antagonists." (PMID 26092545, 2015).